PTH (parathyroid hormone)
Diseases named in the same sentence as PTH in open-access papers (continued):
Sharing a sentence is not in itself a finding about the gene and the disease.
Hypocalcemia (continued). "As NPSP795 rectified the altered signaling responses associated with the Nuf mouse CaSR mutation (Leu723Gln) in vitro, we pursued studies to determine the effects of this calcilytic in Nuf mice, which have hypocalcemia and reduced plasma PTH concentrations." (PMID 33103030, 2020). "Hypoparathyroidism is a rare disease characterized by hypocalcemia with inappropriately low parathyroid hormone (PTH) levels." (PMID 32384131, 2020). "Phosphate retention begins early in CKD and plays a central role in the development of secondary hyperparathyroidism (SPTH) by inducing hypocalcemia, decreasing calcitriol synthesis, and increasing PTH gene expression." (PMID 32961953, 2020). "Many surgeons are interested in predicting early hypocalcemia posttotal thyroidectomy and, therefore, use the intraoperative parathyroid hormone (PTH) and postoperative 1-hour or 4-hour PTH level test." (PMID 32802056, 2020). "Findings were not significant for the relation of urine Ca/creatinine ratio to hyperphosphatemia, high serum PTH, and hypocalcemia." (PMID 33371520, 2020). "Accordingly, the purpose of this study was to evaluate the effect of preoperative VDD on severity of hypocalcemia in patients with acute hypoparathyroidism, defined as an initial postoperative PTH level <15 pg/mL after total or completion thyroidectomy." (PMID 32774362, 2020). "Abnormalities in mineral metabolism also persist after transplantation; in a registry study of 1237 European children, 19% had hypocalcaemia and 40% had a high PTH 3 years after transplantation (interquartile range 1.1–6.2 years)." (PMID 31240395, 2020). "PTH is an 84-amino acid polypeptide secreted in response to hypocalcemia via calcium-sensing receptors (CaSR) present on the surface of the parathyroid glands." (PMID 32823917, 2020). "In patients with transient hypocalcemia, the postoperative day 1 serum PTH and Ca levels were significantly reduced (PTH from 51.89 to 10.30 pg/ml (80.15% reduction)) and Ca was decreased from 2.34 to 1.88 mmol/l (19.51%, reduction; p < 0.01)." (PMID 32802056, 2020). "Biochemical studies show hypocalcemia, hypophosphatemia, and elevated serum levels of alkaline phosphatase and parathyroid hormone." (PMID 32596195, 2020). "After 1 month of treatment, serum phosphorus normalized with a marked reduction of serum PTH, however, the hypocalcaemia persisted." (PMID 33004071, 2020). "This led to the revelation of a vivid biochemical profile of hypoparathyroidism with hypocalcemia, hyperphosphatemia, and low serum intact parathyroid hormone (PTH), and extensive calcification in the brain." (PMID 33133833, 2020). "Frequent monitoring of serum Ca and PTH levels after surgery is reliable for predicting postoperative hypocalcemia." (PMID 32802056, 2020). "The identification of parathyroid glands (PTGs) in thyroid surgery is crucial to avoid postoperative hypocalcemia as a consequence of the missing parathyroid hormone." (PMID 32365790, 2020). "The significant findings in our study were that the various PTH level reduction thresholds predicted transient hypocalcemia in different cohorts." (PMID 32802056, 2020). "Hypoparathyroidism is characterized by low serum concentrations of parathyroid hormone (PTH), which results in hypocalcemia and hyperphosphatemia." (PMID 32555995, 2020). "A similar disease term called pseudohypoparathyroidism (PsHP), showing resistant to PTH, is also characterized by hypocalcemia." (PMID 33015068, 2020). "Similar situation recurred for a total of 5 times and she was diagnosed with PHP by the local hospital due to hypocalcemia, hyperphosphatemia, elevated serum PTH, and multiple intracranial calcification." (PMID 32481259, 2020). "The sign of permanent PSHP is hypocalcemia in combination with low levels of PTH during 6 months or more after surgery." (PMID 34513060, 2020).
Hypocalcemia (continued). "Updated reports on the postoperative PTH levels for predicting hypocalcemia increased pressure for early discharge of patients and freed patients from unnecessary Ca supplements." (PMID 32802056, 2020). "Commonly encountered dysregulation in mineral metabolism during AKI includes hypocalcemia, hyperphosphatemia, elevated parathyroid hormone (PTH), decreased 1,25-dihydroxyvitamin D (1,25D), elevated fibroblast growth factor 23 (FGF23), and decreased klotho." (PMID 33634055, 2020). "In previous reports, hypocalcemia, caused by hyperphosphatemia and reduced 1,25(OH)2D in CKD, inactivated CaSR in PTGs and increased PTH secretion." (PMID 32517664, 2020). "CASR encodes the calcium-sensing receptor (CaSR), responsible for increasing secretion of PTH during hypocalcemia." (PMID 32986719, 2020). "Secondary hyperparathyroidism (SHPT) is related to chronic hypocalcemia, which stimulates PTH secretion." (PMID 32751307, 2020). "PTH and hypocalcemia stimulate the AC-PKA-cytochrome P27B1 (CYP27B1) pathway-mediated hydroxylation of 25-hydroxyvitamin D (25-(OH)D) into the active form (1α,25-(OH)2D)." (PMID 32751307, 2020). "Secondary hyperparathyroidism is a common complication of CKD and it is attributed to hyperphosphatemia, hypocalcemia, reduced vitamin D synthesis as well as PTH skeletal resistance." (PMID 33180791, 2020). "The biochemical hallmarks of hypoparathyroidism are hypocalcemia and hyperphosphatemia in the setting of a low or inappropriately normal level of intact PTH in the serum." (PMID 33133833, 2020). "These foals were hypocalcemic, typically hyperphosphatemic, and had low or normal parathyroid (PTH) concentrations despite hypocalcemia, suggesting hypoparathyroidism." (PMID 32986719, 2020). "Eighteen percent of patients (N=9) developed postoperative hypocalcemia (three patients (6%) were symptomatic); postoperative serum calcium ranged from 3.5 to 5.6 (4.8±0.6), and postoperative PTH ranged from 2 to 52 pmol/L (22.2±10.1)." (PMID 33364096, 2020). "Heritable hypoparathyroidism (HPT) is a genetically heterogeneous disease, characterized biochemically by hypocalcaemia, hyperphosphatemia, low plasma parathyroid hormone (PTH) concentrations and inappropriately normal or high urinary calcium excretion." (PMID 31961795, 2020). "The development of hypomagnesemia inhibits the release and induces peripheral resistance to parathyroid hormone, leading to hypocalcemia." (PMID 32570709, 2020). "The parathyroid gland was stimulated by hypocalcemia and hyperphosphatemia for a long time, and it was easy to secrete a large amount of parathyroid hormone; subsequently, parathyroid hyperplasia was observed." (PMID 32049851, 2020). "Hypoparathyroidism is characterized by low or inappropriately normal levels of parathyroid hormone leading to hypocalcemia." (PMID 32493404, 2020). "Our findings show that NPSP795 elicits dose‐dependent increases in PTH and ameliorates the hypocalcemia in an ADH1 mouse model." (PMID 33103030, 2020). "A significant difference was seen in the postoperative day 1 serum PTH level in patients with normocalcemia and hypocalcemia (22.06 vs. 6.35 pg/ml, p < 0.001)." (PMID 32802056, 2020). "Pseudohypoparathyroidism (PHP) represents a group of disorders characterized by resistance to the parathyroid hormone (PTH) leading to hypocalcemia and hyperphosphataemia." (PMID 32224912, 2020). "The hyper activated PTH is considered to deteriorate bone mechanical properties, to rescue the state of hypocalcemia among ESRD patients, on the expense of changing bone structure and reducing bone mass." (PMID 33180791, 2020). "Early-onset hypocalcemia is caused by an increased reduction in the serum calcium level that physiologically occurs within the first three days in newborns, and delayed PTH secretion in response to hypocalcemia." (PMID 31320908, 2019).
Hypocalcemia (continued). "Preoperative PTH levels are unreliable for predicting postoperative hypocalcemia because low levels of vitamin D lead to higher preoperative PTH levels due to secondary hyperparathyroidism." (PMID 31340251, 2019). "In particular, low ioPTH and postoperative PTH levels correlate with early recognition of postoperative hypocalcemia, allowing for timely intervention via supplemental calcium and calcitriol administration." (PMID 31781035, 2019). "Enhanced PTH secretion occurs in response to hypocalcemia, hyperphosphatemia, and/or a decrease in serum 1,25-dihydroxyvitamin D (1,25(OH)2D) level, whereas high serum levels of calcium, calcitriol, or FGF23 suppress PTH secretion." (PMID 31637056, 2019). "The increased maternal calcium due to maternal hyperparathyroidism passes to the infant through the placenta and suppresses fetal PTH synthesis and impairs PTH response to postpartum hypocalcemia." (PMID 31320908, 2019). "Hypomagnesemia can cause impaired PTH secretion and reduced peripheral response to PTH, leading to hypocalcemia." (PMID 31320908, 2019). "Hypocalcemia is a known side effect of this drug along with compensatory increase in parathyroid hormone (PTH)." (PMID 31016056, 2019). "Reduced serum levels of 1,25-dihydroxyvitamin D lead to hypocalcemia on top of positive phosphate balance, both stimulating PTH release and eventually leading to secondary hyperparathyroidism." (PMID 30805347, 2019). "It has been shown that elevated PTH resulting from hypocalcaemia mediates the induction of CYP27B1, which in turn stimulates the synthesis of 1,25(OH)2D3 via the nuclear orphan receptor 4A2, also known as NURR1." (PMID 30393837, 2019). "In HDR, hypoparathyroidism is characterized by either symptomatic or asymptomatic hypocalcemia along with undetectable or low serum levels of parathyroid hormone (PTH)." (PMID 31660939, 2019). "The increase in the synthesis of 1α,25(OH)2D3 in response to hypocalcemia (via the secretion of parathyroid hormone) occurs within a few hours, whereas the parathyroid glands respond to hypocalcemia within a few minutes." (PMID 31387330, 2019). "The endocrine studies showed that she has hypocalcemia (2.21 mmol/l) and hypophosphatemia (0.99 mmol/l) but normal parathyroid hormone levels (5.2 pmol/l)." (PMID 31297990, 2019). "We present a patient with ESRD on peritoneal dialysis who developed severe symptomatic hypocalcemia and dramatic increase in PTH following denosumab therapy." (PMID 31016056, 2019). "Hypocalcemia and high parathyroid hormone (PTH) are regarded as classical marks of hypovitaminosis D, but their associations with vitamin D deficiency have never been investigated in the general population." (PMID 31374914, 2019). "In our study, we evaluated the serum calcium on 1st, 2nd and 5th postoperative day to predict post thyroidectomy hypocalcaemia an alternative to quick PTH level due to limited resources and high cost of PTH." (PMID 30881435, 2019). "Hypoparathyroidism is an uncommon disorder that is characterized by hypocalcemia and hyperphosphatemia due to low or inappropriately normal serum levels of parathyroid hormone (PTH)." (PMID 30540559, 2019). "Extensive research has been done on the value of the parathyroid hormone (PTH) in predicting post-thyroidectomy hypocalcemia." (PMID 31281762, 2019). "Phosphate retention, low calcitriol levels, and the tendency to hypocalcemia stimulated PTH secretion, which promoted calcitriol production and inhibited calcium excretion through the kidneys, and also increased calcium and phosphate efflux from the bones." (PMID 30909513, 2019). "Hypocalcemia markedly increases PTH secretion with consequent increases in calcitriol concentrations that in turn inhibit PTH synthesis." (PMID 31508432, 2019). "In our case, we found the patient’s PTH levels to be extremely high with mild hypocalcemia, normal phosphorous levels and low vit." (PMID 31102836, 2019).
Hypocalcemia (continued). "Pseudohypoparathyroidism (PHP) is a rare disease, characterized by hypocalcaemia with a high level of parathyroid hormone (PTH) due to PTH resistance in the target organs." (PMID 31892351, 2019). "In cases with elevated serum phosphate levels and increased PTH levels in response to hypocalcemia, excessive exogenous intake of phosphate, renal failure, and pseudohypoparathyroidism (PTH resistance) should be considered." (PMID 31320908, 2019). "It is characterized by end-organ resistance to PTH, resulting in hypocalcemia and hyperphosphatemia." (PMID 31892351, 2019). "In fact, hyperglycemia leads to hypocalcemia by increasing urinary calcium excretion, impairing the vitamin D status, and interfering with the parathyroid hormone (PTH) and vitamin D axis, moreover, it induces a chronical inflammatory state." (PMID 31075971, 2019). "HypoPT has been clearly defined in the guidelines on 'Treatment of chronic hypoparathyroidism in adults' by ESE as ‘a disease with hypocalcaemia and inappropriately low parathyroid hormone (PTH) levels’." (PMID 31176307, 2019). "The presence of severe hypocalcaemia and elevated PTH with a marginally low vitamin D level and especially the basal, thalamic and dentate ganglia calcification suggests the diagnosis of pseudohypoparathyroidism." (PMID 31856822, 2019). "Vitamin D deficiency is a cause of secondary hyperparathyroidism, and therefore the capacity of PTH levels in the postoperative period to act as a predictor of hypocalcemia probably depends on the preoperative vitamin D level." (PMID 31340251, 2019). "The accumulation of phosphate contributes to hypocalcemia by producing skeletal resistance to the calcemic action of PTH." (PMID 30909513, 2019). "The PTH level is elevated in response to hypocalcemia, and calcium and phosphate absorption is impaired." (PMID 31320908, 2019). "If the PTH level is elevated in response to hypocalcemia, the parathyroid glands are considered working normally, and serum phosphate levels should be evaluated for differential diagnosis." (PMID 31320908, 2019). "Hypocalcemia was rapidly corrected by substitution, but the endogenous serum parathyroid hormone (PTH) remained low." (PMID 30791949, 2019). "The decrease of PTH level by parathyroidectomy in SHPT patients exposed cinacalcet can significantly diminish mobilization of skeletal calcium with concomitant hypocalcaemia and hyperkalaemia." (PMID 31221111, 2019). "In PHP end organ resistance to PTH results in hypocalcaemia, hyperphosphataemia and high PTH levels." (PMID 31856822, 2019). "On suspicion of hyperparathyroidism due to persistent hypocalcemia and hyperphosphatemia, parathyroid hormone (PTH) titration was requested, with a result of 00.90 pg/mL (normal value 12‐88)." (PMID 31624612, 2019). "The nodular or adenomatous parathyroid glands begins to function autonomously and continue to secrete PTH even if hypocalcemia is corrected." (PMID 31014177, 2019). "Although hypoparathyroidism is suspected on clinical grounds, its diagnosis is based on laboratory tests demonstrating inappropriately low PTH levels in the presence of hypocalcemia (A)." (PMID 29694629, 2018). "In many other studies, a decrease in blood PTH following TT was found to result in possible development of temporary hypocalcemia." (PMID 30092793, 2018). "Hypocalcemia can also enhance renal 1α-hydroxylase activity, but much of this effect is mediated indirectly through PTH." (PMID 30513912, 2018). "Parathyroid hormone (PTH) is an 84 amino acid hormone produced in response to hypocalcemia, and its primary role is to increase serum calcium levels to restore ion balance." (PMID 29725836, 2018). "The first biochemical abnormalities to become apparent are elevated serum levels of PTH and elevated serum levels of phosphorus, followed by hypocalcaemia." (PMID 29959430, 2018).
Hypocalcemia (continued). "In order to study the effect of FGFRi on PTH secretion in the setting of hypocalcemia, we administered the FGFRi PD173074 or vehicle prior to induction of acute hypocalcemia by EGTA infusion." (PMID 29063159, 2018). "Another well-known source of hypocalcemia with low PTH levels is autosomal dominant hypocalcemia (ADH) triggered by an activating mutation in the genes encoding the calcium-sensing receptor (CaSR) mainly placed in the parathyroid glands." (PMID 29971010, 2018). "Dysfunction of parathyroid hormone is highly prevalent in critical illness, and hypocalcemia is common in critically ill patients." (PMID 30046608, 2018). "Secondary hyperparathyroidism in advanced CKD results from multiple stimuli, including hyperphosphatemia, hypocalcemia, low 1,25(OH)D levels, and skeletal resistance to PTH." (PMID 30109232, 2018). "Abolishment of an inhibitory effect during hypocalcemia is known from other endocrine regulatory mechanisms as it has been demonstrated for calcitriol’s regulation of PTH transcription." (PMID 29063159, 2018). "These lower active vitamin D levels, in conjunction with resulting hypocalcemia, stimulate a subsequent increase in PTH." (PMID 30109232, 2018). "Based on our data, decreased PTH during the first 24 h after surgery was a statistically reliable predictor of post-operative hypocalcemia (p < 0.001)." (PMID 30092793, 2018). "In hypocalcemia, when increased PTH secretion is needed to restore the calcium homeostasis, this inhibitory effect of FGF23 is abolished." (PMID 29063159, 2018). "Pseudohypoparathyroidism (PHP) is a rare heterogeneous disease characterized by hypocalcemia and hyperphosphatemia due to resistance to parathyroid hormone (PTH) in target organs." (PMID 30060753, 2018). "Elevations in fibroblast growth factor 23 (FGF23) and increased secretion of parathyroid hormone (PTH) help to prevent the accumulation of phosphate and hypocalcemia." (PMID 30513703, 2018). "Laboratory tests showed hypokalemic alkalosis, hypomagnesemia, hypocalcemia and secondary hyperaldosteronism, as well as hypocalciuria and transient decreased PTH." (PMID 30558554, 2018). "The literature describes several protocols for measurement of serum PTH levels, with variations in the time of blood collection, criteria for the diagnosis of hypocalcemia, number of collected blood samples, and different PTH cutoff levels." (PMID 29694629, 2018). "In pseudohypoparathyroidism, the production of PTH by the parathyroids is normal, and the biochemical disorder resulting from hormonal resistance (hypocalcemia and hyperphosphatemia) stimulates increased PTH production." (PMID 29694629, 2018). "In acute hypocalcemia, when increased PTH secretion is needed to restore the calcium homeostasis, this inhibitory effect of FGF23 is abolished." (PMID 29063159, 2018). "The occurrence of hypomagnesemia should be considered in all patients with hypocalcemia and low or inappropriately normal PTH levels." (PMID 29694629, 2018). "Highlights SBEM: Hypoparathyroidism is suspected on clinical grounds, but its diagnosis is based on laboratory tests indicating inappropriately low PTH levels in the presence of hypocalcemia (A)." (PMID 29694629, 2018). "This condition is caused by genetic defects in postreceptor PTH signaling and is characterized in laboratory tests by hypocalcemia and hyperphosphatemia in the presence of elevated PTH levels in patients with normal renal function (A)." (PMID 29694629, 2018). "While it is hard to predict the severity and duration of hypocalcemia with hungry bone disease, most patients have high pre-surgery PTH levels." (PMID 30109232, 2018). "Hypoparathyroidism is suspected on clinical grounds but is diagnosed based on laboratory tests indicating inappropriately low PTH levels in the presence of hypocalcemia." (PMID 29694629, 2018).